TNF (tumor necrosis factor)
Diseases named in the same sentence as TNF in open-access papers (continued):
Sharing a sentence is not in itself a finding about the gene and the disease.
colitis (continued). "CW supplementation inhibits the high levels of inflammation induced by DSS, suppressing excessive inflammatory mediators (serum TNF‐α, IL‐1β, and IL‐6), downregulating the overexpressed mRNA levels of TNF‐α, IL‐1β, IL‐6, TLR4, and iNOS, while upregulating IL‐10, thereby alleviating colitis." (PMID 39830908, 2025). "In addition, I3C therapy significantly reduced the mRNA expression of proinflammatory cytokines IL‐1β, IFNγ, and TNFα in DSS‐induced colitis mice." (PMID 40410944, 2025). "At the same time, the results of SAKAI showed that AST could inhibit the expression of inflammatory factors (IL-1β, IL-6, TNF-α, and COX-2) in mice and ultimately alleviate the development of colitis." (PMID 40867814, 2025). "In a Salmonella-induced colitis model, BB-12 was shown to alleviate inflammation by modulating the relative expression of the colonic cytokines IL-1β, TNF-α and CXCL2, and reducing the secretion of IL-1β, IL-6, and TNF-α in serum and colonic tissues." (PMID 40673154, 2025). "Moreover, levels of pro-inflammatory cytokines including IL-6, IL-1β, and TNF-α were notably reduced, whereas anti-inflammatory cytokine IL-10 was notably increased after YTA treatment in colitis mice." (PMID 41476793, 2025). "Our previous research confirmed that corn protein hydrolysate with glutamine-rich peptides effectively regulates cytokine levels, including reducing the pro-inflammatory cytokines IL-1β, IL-6, and TNF-α and increasing the anti-inflammatory cytokine IL-10, to improve DSS-induced colitis in mice." (PMID 40290078, 2025). "In addition, ligustilide inhibited the TNF-α signaling pathway, evidenced by a dose-dependent decline of TNF-α content in LPS-stimulated RAW264.7 cells and colitis mice." (PMID 40904624, 2025). "Considering that anti-TNF-α immunotherapy, while employed in IBD, is not universally effective and that newer therapies targeting IL-23R or IL-17, which play a detrimental role in colitis, are costly, iTcES represents a promising biotherapeutic alternative." (PMID 40576745, 2025). "In a DSS-induced experimental colitis model in rats, PNS demonstrated the ability to suppress the PI3K/Akt signaling pathway, reduce oxidative stress, and lower pro-inflammatory cytokines such as IL-6, IL-1β, and TNF-α." (PMID 40417220, 2025). "Furthermore, it decreased pro-inflammatory cytokines (IL-6, IL-23, and TNF-α) and STAT3 pathway phosphorylation, leading to IL-17 silencing and suppression of colitis." (PMID 41465447, 2025). "The marked suppression of TNF-α and CRP in the HDP group is consistent with findings in rodent models, where postbiotics downregulated NF-κB signaling and mitigated cytokine storms in inflammatory conditions such as colitis." (PMID 41209733, 2025). "Furthermore, compared with the control group, RT-PCR revealed that there was an obvious increase in the expression of the typical inflammation-related cytokines, mainly including TNF-α, IL-6, IL-1β, and iNOS in the DSS-induced colitis model." (PMID 40255504, 2025). "In contrast to our results, other studies indicate an anti-inflammatory role for 17 HDHA, with negative correlations observed with IL-1β and other cytokines and adhesion molecules such as TNF-α, MIP-2, CXCL1/KC, VCAM-1, ICAM-1, and LFA-1 in an animal model of colitis." (PMID 41009650, 2025). "Moreover, FMT significantly reduced the expression of TNF-α and IL-6 in colon tissues in ICB+DSS-induced colitis mice." (PMID 39895628, 2025). "In addition, IQW has also been shown to enhance the intestinal immunological barrier by reducing TNF-α and IL-17 levels in a mouse model of DSS-induced colitis, which is a novel option for the prevention of inflammatory bowel disease." (PMID 40290078, 2025). "Indeed, increased concentrations of IL-1β, TNF-α, and IFN-γ in DSS colitis was accompanied by the expansion of functional MDSCs." (PMID 40244120, 2025).
colitis (continued). "In addition, the use of clinically available TNF inhibitors in combination with CTLA-4 and PD-1 immunotherapy in mice has been found to alleviate colitis and improve anti-tumor efficacy." (PMID 40797218, 2025). "Thus, the levels of NO, TNF-α, IL-6, and PGE2 in the colon tissue of LPS-induced Caco-2/RAW264.7 cells and DSS-induced colitis mice were decreased." (PMID 39202931, 2024). "Therefore, we used flow cytometry to examine the frequency of TNF-α produced by mucosal macrophages and systemic neutrophils in DSS-induced colitis in the absence or presence of DJ-X-013." (PMID 39255739, 2024). "Besides, 3-MA increased the proinflammatory factors levels (TNF-α, IL-6, IFN-γ, IL-22) in ANI/NEO-treated mice with DSS-induced colitis." (PMID 38354108, 2024). "The qRT‐PCR results demonstrated significantly elevated levels of pro‐inflammatory factors (IL‐6 and TNFα) in colons of the colitis animal model, while no significant change in the levels of anti‐inflammatory cytokines (IL‐10) was observed." (PMID 38340032, 2024). "Studies conducted on mice with colitis have demonstrated that intact CPP is more efficacious in reducing the expression of pro-inflammatory factors IL-6, CXC motif chemokine ligand 2 (CXCL2), IL-1β, and TNF-α than a single CPP extract." (PMID 39839098, 2024). "The extract effectively improved the reduction in body weight and the clinical manifestations of colitis, significantly ameliorated the clinical signs observed in UC, and decreased cytokine levels from the Th1 (IFN-γ, IL-12, and TNF-α) and Th17 (IL-6 and IL-17) immune response pattern." (PMID 39195452, 2024). "However, their immunomodulatory capacity and were particularly enhanced in cADSCs primed with a combination of the inflammatory cytokines TNF-α and IFN-γ and in cADSCs primed with colon homogenate from colitis mice." (PMID 39176394, 2024). "Furthermore, in colitis mice treated with hUC-MSCs, there was a notable decrease in serum levels of IFN-γ, IL-1β, TNF-α and IL-6, as well as reduced the mRNA expression levels of Ifng, Il1b, Tnfa and Il6 in the colons." (PMID 38956621, 2024). "Interestingly, when we treated the infected colitis mice with LGG or BL, we observed a significant increase in IL-6, CXCL2, IL-1β, TNF-α, IL-17a, and IL-22 gene expression in the cecal tissue, indicating an enhanced inflammatory response." (PMID 38397855, 2024). "Also, these compounds possess anti-inflammatory properties, suppressing inflammatory pathways involved in colitis and inhibiting the NLRP3 inflammasome, thereby reducing pro-inflammatory cytokines like IL-1β, IL-6, and TNF-α." (PMID 39061864, 2024). "Lactiplantibacillus plantarum HF05 could reduce the release of TNF-α and IL-6 from LPS-treated macrophages and the levels of TNF-α and IL-6 in DSS-induced colitis mice, thereby playing an anti-inflammatory role." (PMID 39594091, 2024). "Also, sinapic acid reduces serum levels of proinflammatory cytokines (TNF-α, IL-1β, IL-6, IL-17α, IL-18, and interferon (IFN)-γ) and increases anti-inflammatory cytokines (IL-4 and IL-10) in Kunming mice with DSS-induced colitis." (PMID 38732594, 2024). "Although TNF-α antagonists (infliximab, etanercept, adalimumab and certolizumab) have also been used as rescue therapy for ICI-induced colitis, arthritis and pneumonitis, controversial preclinical and clinical data about the effect of TNF-α antagonists on patients survival are currently available." (PMID 38443899, 2024). "Enrichment analysis showed that pathways such as TNF-α signaling via NFκB, IFN-γ responses, and inflammatory responses were enriched as expected, but surprisingly these pathways were also commonly enriched upon priming with colitis tissue." (PMID 39176394, 2024). "Moreover, genetically engineered L. lactis strains harboring and delivering anti-TNF nanobody, ovalbumin, DQ8 gliadin epitope, and GAD65 and IL-10 were used as vaccine against colitis, autoimmune diseases, celiac disease, and type 1 diabetes, respectively." (PMID 38495751, 2024).
colitis (continued). "Among the various Th-cell subsets, activation of the Th1/Th17-cell response, characterized by a cytokine profile featuring components such as TNF-α, IFN-γ, interleukin (IL)-6, and IL-17, also contributes to the development of the acute phase of DSS-induced colitis." (PMID 39176394, 2024). "This study found that compared with colitis models induced by DSS, expression levels of NO, TNF-α, IL-1β, and IL-6 were remarkably reduced in the peripheral blood and colon tissues of colitis mice pre-treated by B. tequilensis YB-2, while expression levels of IL-10 and IL-4 significantly increased." (PMID 38998101, 2024). "As a result of colitis, elevated mRNA levels of CD86 and TNF-α were detected." (PMID 38247868, 2024). "Another study found that oral administration of probiotic-fermented red ginseng could significantly relieve the symptoms of colitis in (DSS)-induced mouse mode through downregulating the serum levels of inflammatory factors (IL-6 and TNF-α)." (PMID 38698858, 2024). "After measuring the levels of pro-inflammatory cytokines in the serum of each group of mice, we found that compared to the control group, the levels of TNF-α (p < 0.001), IL-1β (p < 0.01), and IL-6 (p < 0.05) were significantly increased in the serum of mice with DSS-induced colitis." (PMID 38474831, 2024). "In addition to synergistic antitumor effects, of greater interest is the value of TNF blockade in mitigating irAEs, especially IBD-induced colitis." (PMID 39034318, 2024). "In murine DSS-induced colitis, inosine attenuates the hallmarks of colitis and colonic levels of malondialdehyde (MDA), myeloperoxidase activity (MPO), major intrinsic proteins (MIP)-1α and -2 and proinflammatory cytokines IL-1, IL-6, IL-12 and TNF-α." (PMID 38474346, 2024). "Besides elevating the LC3-II/LC3-I ratio, ATG5 and Beclin-1 levels and decreasing P62 level, the ANI/NEO combination decreased the expression of several inflammatory cytokines (INF-γ, TNF-α, IL-6, and IL-22) in colon tissue from mice with DSS-induced colitis." (PMID 38354108, 2024). "Cytokines are important mediators of inflammation and elevated levels of major proinflammatory cytokines such as tumor necrosis factor (TNF), interleukin (IL)-6, IL-1β, and interferon-gamma (IFN-γ) are observed in patients with ulcerative colitis and also in chemically induced colitis models." (PMID 38998493, 2024). "Secondly, B. bifidum has immune-regulatory functions, inhibiting the expression of inflammatory factors interleukin (IL)-1β, tumor necrosis factor (TNF)-α, IL-6, and interferon (IFN)-γ, while promoting IL-10 expression, thus facilitating gut damage repair in colitis mice." (PMID 39525506, 2024). "Additionally, both limonene and terpineol demonstrate anti-inflammatory effects by decreasing the levels of pro-inflammatory cytokines such as TNF, IL-6, leptin, and AOPP in a colitis induction model." (PMID 39456515, 2024). "We also verified that the absence of mPGES-1 leads to higher expression levels of TNFα in TNBS-induced colitis." (PMID 39596393, 2024). "Similarly, five days after the induction of colitis, the untreated TNBS mice demonstrated a significantly increased relative gene expression of TNF in their colons compared to the controls (p < 0.001)." (PMID 38786849, 2024). "Additionally, Q. Yu and team found that SIN (100 and 200 mg/kg) enhanced the weight and survival rate of colitis mice, diminished MPO activity, and downregulated miR-155, c-Maf, TNF-α, and IFN-c." (PMID 38276618, 2024). "Increased expressions of Iba1, a marker of activated microglia, IL-6, TNF-α, and the cyclin-dependent kinase inhibitor p21 (p21) in the hippocampus were detected in the acute phase of DSS-induced colitis, while the overexpression of p21 persisted in the chronic phase." (PMID 38247868, 2024).
colitis (continued). "In addition, the graph illustrates the significant reductions in the IL‐1β, IL‐6, and TNF‐α expression levels following BLF administration, further supporting the anti‐inflammatory effect of BLF in AD mice with colitis." (PMID 38334213, 2024). "Neither TNBS-induced colitis nor dietary intervention had a significant impact on the level of TNFα in the testis (ANOVA, NS)." (PMID 39125425, 2024). "In addition, the mRNA levels of proinflammatory cytokines including Ccl5, IL-17, IL-6, TNF-α, IFN-γ, CXCL10, and Ccl8 were all found to be increased in colitis tissues of S100A4Smad4-/- mice compared with those in Smad4fl/fl mice." (PMID 39664586, 2024). "SNS significantly reduced colonic inflammation, similar to the effects of vagus nerve stimulation (VNS), by modulating autonomic function and cytokine production (decreased TNF-α, IL-6, and IL-17A, increased IL-10), indicating potential therapeutic utility for IBD treatment." (PMID 39605787, 2024). "In vitro and in vivo studies also demonstrated that palmitic acid combined with oleic acid reduced inflammatory markers such as COX-2, TNFα, IL-6, and IL-12 in LPS-stimulated macrophages, and reduced inflammatory parameters in models of dextran sulfate sodium (DSS)-induced colitis in mice." (PMID 39339251, 2024). "In IR62 treatment group, the all selected taxa, but not Muribaculum, exhibited a high correlation with all colitis-related markers except for TNF-α, IL-1β, iNOS, and occludin." (PMID 39849930, 2024). "In a study on DSS-induced colitis in mice, CSCC exhibited powerful anti-inflammatory effects by inhibiting the JNK1/STAT3 signaling pathway, reducing the levels of pro-inflammatory cytokines TNF-α, IL-1β, and IL-17." (PMID 39329121, 2024). "At present, DPP-4 inhibitors are used to treat experimental mice colitis (DSS-induced mice colitis and TNBS-induced mice colitis), and their mechanism may be inhibiting IL-6 and TNF-α." (PMID 37554552, 2023). "In addition, live probiotic L. johnsonii suppressed TNF and IL-1β expression and stimulated anti-inflammatory cytokine (IL-10) expression in the colon of trinitrobenzenesulfonic acid (TNBS)-induced colitis mice." (PMID 36986118, 2023). "Consistent with previous reports demonstrating the anti-inflammatory effects of atractylodin in numerous inflammatory models, we observed clear anti-inflammatory effects of atractylodin against TNF-α-induced cellular inflammation and DSS-induced colitis in mice." (PMID 36614242, 2023). "Loading TNF-α with GELNs can downregulate NLRP3, caspase-1, IL-1β, TNF-α, IL-6 and IL-1b, upregulate anti-inflammatory substances such as IL-10 and IL-22 in colon tissue of DSS-induced colitis mice." (PMID 37033644, 2023). "Finally, the mouse model of colitis was established and SOD, MDA, TNF-α, IL-1β, IL-6 and P38 as well as ERK were detected from mice." (PMID 38024351, 2023). "Other studies report that resveratrol reduces inflammation in patients with UC to improve their quality of life and disease clinical colitis activity, and in animal models of IBD, where there are reduced pro-inflammatory markers (TNF-α, IFN-γ, IL-1β, IL-6, and IL-4) and DAI." (PMID 37660064, 2023). "Considering that IL-6 expression was upregulated in naïve Cldn3KO mice, we further examined whether the production of TNF-α, a proinflammatory cytokine targeted in treating IBD, is also altered in Cldn3KO mice under conditions of colitis." (PMID 38010872, 2023). "Furthermore, PELNs demonstrated the ability to suppress the expression of pro-inflammatory cytokines (IL-6, IL-12, IL-1β, and TNF-α) and MPO, and increase the levels of the anti-inflammatory cytokine IL-10, thereby alleviating DSS-induced colitis in mice." (PMID 37653406, 2023).
colitis (continued). "These anti-inflammatory effects were corroborated by animal studies, which showed that a daily supplementation of bergamot juice extract in a mice experimental colitis model significantly decreased the IL-1β, NK-kbp65, p-JNK, TNF-α colon levels, and the nitrotyrosine positive staining degree." (PMID 36672947, 2023). "Nevertheless, though the CD3+Foxp3+ MLN cells were decreased, the concomitant reduction in IL-10 producing lymphocytes at these draining lymph nodes, together with an outstanding splenic TNF production, reiterates the pro-inflammatory potential of MLT in experimental colitis." (PMID 36838425, 2023). "Our analysis showed that Butyricimonas had a negative correlation with proinflammatory cytokines, such as TNF-α and MPO, indicating that it may be effective in the progression of colitis." (PMID 37047694, 2023). "Therefore, we assessed the serum level of cytokines at the end of our colitis experiments, and found that IFN-γ, TNF, IL-2, IL-6, and IL-17 levels were all much higher in DSS-induced colitis mice than in control mice." (PMID 37275854, 2023). "In addition, the levels of oxidative stress (MPO, SOD, and MDA) and inflammatory cytokines (TNF-α, IL-1β, IL-6, and IL-10) were reversed by PHI in colitis mice." (PMID 36768559, 2023). "NF-kB through TNF-alpha activation has a pivotal role in the IBD pathology and recurrence and as its suppression could result in colitis remission both in the experimental and clinical settings." (PMID 37275758, 2023). "On the contrary, excessive consumption of oleic acid-rich extra virgin olive oil failed to ameliorate symptoms in DSS-induced colitis mice and even elevated TNF-α levels." (PMID 37868958, 2023). "Vedolizumab therapy in ICI-induced steroid-refractory colitis or non-responders to anti–TNF-α;Early introduction (within 10 days of the onset) of VDZ and sustained 3 or more infusions.Available for tuberculosis patients." (PMID 37404814, 2023). "Subsequently, we further analyzed the level of inflammatory factors in colon tissue and found that the pro-inflammatory cytokines IL-1β, IL-6, IL-12, IL-17 and TNF-α were increased and the anti-inflammatory cytokine IL-10 was decreased in the colon of DSS-induced colitis." (PMID 37438752, 2023). "Besides, consistent with the in vitro results, pro-inflammatory cytokine levels (including IL-1β and TNF-α) in the colon tissues and blood serum were lower in the PEG-CNPs group than in the colitis group." (PMID 37507801, 2023). "In order to confirm whether HeHi_Lp administration also affects the gene expression of inflammatory cytokines, the mRNA expression of TNF-α, IL-6, and IL-1 was measured in the colon tissue of mice with DSS-induced colitis using real-time PCR." (PMID 37891901, 2023). "However, expanded T cell reaction and the production of significant levels of inflammatory cytokines, such as TNF-α, were noted after the induction of DSS experimental colitis in mice." (PMID 37167242, 2023). "Preclinical studies supported the effectiveness of anti-IL-1β monoclonal antibodies 7F IgG and FL-BsAb1/17 in mitigating colitis, while anakinra showed efficacy in the UC model of primary anti-TNF non-responders." (PMID 38274809, 2023). "In mice with CMI and colitis, VNS significantly reversed the increases in blood–brain barrier permeability, infarct volume, activation of Iba-1+ microglia and GFAP+ astrocytes, and TNF-α level in mice with colitis and CMI." (PMID 37484689, 2023). "Colonic levels of myeloperoxidase, IL-6, and TNF-α decreased significantly in rats treated with the mixture, while a significant decrease in (Toll-like receptor) TLR-4 mucosal gene expression and a significant improvement in colitis were observed." (PMID 37569412, 2023). "Mechanistically, priming with IFN-γ and TNF-α enhanced TSG-6 production through IDO-mediated tryptophan catabolism along the KYN pathway, thereby endowing MuSCs with more powerful therapeutic potency in DSS-induced colitis." (PMID 37507432, 2023).